SEMA3F (semaphorin 3F)
Diseases named in the same sentence as SEMA3F in open-access papers (continued):
Sharing a sentence is not in itself a finding about the gene and the disease.
tumor (continued). "In human tissue samples, immunohistochemical staining detected SEMA3F expression in the normal intestinal tissue adjacent to the tumor." (PMID 26447612, 2015). "Circulating serum levels of SEMA3F protein peaked on day 8 following administration of adenovirus (day 10 post injection of tumor cells), and persisted until the end of the experiment on day 14 (average of 26 ng/ml, n = 4)." (PMID 26156437, 2015). "Consistent with our findings, Id proteins has been shown to enhance tumor migration and invasion by upregulation of metalloproteinases and semaphorin 3F." (PMID 24659686, 2014). "Class 3 semaphorins, Sema3B and Sema3F, are secreted proteins that regulate angiogenesis, tumor growth, and metastasis by binding to their transmembrane receptor complex consisting of plexins and neuropilins." (PMID 24065959, 2013). "On the other hand, reducing SEMA3F expression has little effect on tumor growth, suggesting that the tumor suppressor function of RORα involves other target genes and pathways as well." (PMID 23443091, 2012). "The np2agonist sema3F also inhibited tumor formation effectively although somewhat less effectively than sema3E and sema3D." (PMID 22936999, 2012). "SEMA3F is a tumor-suppressive microenvironmental factor that is often inactivated in metastatic cancer." (PMID 23443091, 2012). "Then, some studies reported that Sema3F can even induce apoptosis in cancer cells as well as tumor suppression in various xenograft experiments." (PMID 24212788, 2011). "In conclusion, we have found for the first time that the semaphorins sema3A, sema3D, sema3E and sema3G possess anti-tumorigenic and anti-angiogenic properties similar to those displayed by the previously identified tumor suppressor sema3F." (PMID 18818766, 2008). "Sema3B and sema3F were previously characterized as tumor suppressors and as inhibitors of tumor angiogenesis." (PMID 18818766, 2008). "SEMA3F acts as a tumour suppressor gene by reducing angiogenesis and metastasis, probably through the inhibition of integrin-mediated adhesion and VEGF expression." (PMID 18781179, 2008). "Subsequently, the SEMA3F gene was found to be a tumor suppressor." (PMID 41391772, 2025). "Similarly, changes in the distribution patterns of vimentin in the control tumors, which only labels myoepithelial cells, and in the tumors over-expressing SEMA3F, which is widely distributed in the tumor mass, have been observed." (PMID 39138514, 2024). "Overexpression of SEMA3F led to an increase in both tumor weight and tumor volume." (PMID 39138514, 2024). "Although SEMA3F has been extensively reported to act as a tumor suppressor element by inhibiting cell migration in the context of metastasis, two recent publications point to a prometastatic role of SEMA3F in hepatocarcinoma, thus suggesting that SEMA3F is a suitable poor prognosis marker." (PMID 39138514, 2024). "Additionally, in vivo studies established that the induction of SEMA3F expression resulted in the inhibition of the tumor growth, as well as a significant reduction in tumor lymphangiogenesis and lymph node involvement." (PMID 35565388, 2022). "Semaphorin-3F (Sema3F) is known as a negative regulator of tumor angiogenesis." (PMID 33081056, 2020). "In tumor cells these transcription factors can be activated by inflammation, and similar pathways might be at play in ECs in regulating SEMA3F expression." (PMID 32098168, 2020). "Moreover, immunohistochemistry assay revealed that downregulation of SEMA3F countervailed the effect of FAM83C-AS1 sponging on the expression of Ki67, PCNA, E-cadherin and N-cadherin, indicating that SEMA3F depletion promoted tumor growth and EMT process." (PMID 33109776, 2020). "Similarly, the over-expression of MYC in metastatic tumor cells leads to the up-regulation of Id2 and, hence, to the repression of SEMA3F." (PMID 33081056, 2020).
tumor (continued). "Lower mRNA expression of SEMA3B, SEMA3D, SEMA3G, and PLXNA2 or higher mRNA expression of SEMA3F, NRP1, ITGB3, ITGA5, and VEGFA genes were detected in the older patient group and associated with the higher tumor grade, wild-type status of IDH, and lower rate of survival time (p < 0.05)." (PMID 33036421, 2020). "Therefore, the function of SEMA3F as a tumor promotor or tumor suppressor still needs to be further studied." (PMID 32241267, 2020). "Correlations between higher levels of SEMA3A, SEMA3C, and SEMA3F and type 1, 2, and 6 infiltrates (C1, C2 and C6), indicated a tumour promoter role of these gene members, as patients belonging to those categories had worse survival characterized with higher proliferation rate and enriched with TGFβ." (PMID 32241267, 2020). "Moreover, downregulation of SEMA3F rescued the suppressive effect of FAM83C-AS1 on tumor growth, volume and weight." (PMID 33109776, 2020). "Although promising, these in vivo findings leave open the question of whether local or systemic administration of the soluble forms of Sema3A, Sema3D, Sema3E, or Sema3F may recapitulate the tumor-suppressing effect of ectopically expressed molecules." (PMID 31052281, 2019). "Indeed, both sema3F and sema3C have been observed to inhibit tumor lymphangiogenesis as well as tumor metastasis mediated by lymphatics." (PMID 30696103, 2019). "Similarly, Sema3F expression in endothelial cells also induced apoptosis while expression in vascular and lymphatic endothelial cells provided anti-tumour properties." (PMID 29854302, 2018). "Moreover, PI-3K, a regulator of Akt, is also deactivated by SEMA3F in tumor and ECs, suggesting that SEMA3F is a powerfull inhibitor of the PI-3K-Akt-mTOR signaling pathway." (PMID 30532711, 2018). "On the other hand, the expression of SEMA3F is downregulated in highly metastatic tumor cells." (PMID 30532711, 2018). "Indeed, Sema3f inhibits angiogenesis, metastasis and motility of primary tumor cells, and decreased expression of Sema3f is correlated with advanced disease stages and more aggressive tumors in human NSCLC, indicating its important role in lung carcinogenesis." (PMID 29254206, 2017). "This suggests that SEMA3F is a candidate tumor suppressor in the pathogenesis of OSCC." (PMID 29299034, 2017). "We tested the function of SEMA3F, as a putative tumor suppressor, in SAS and HSC2 cell lines." (PMID 29299034, 2017). "The expression of SEMA3F in cancer cells inhibits tumor growth, invasion and metastasis." (PMID 29299034, 2017). "The function of SEMA3F in OSCC tumor formation was also assessed in vivo." (PMID 29299034, 2017). "SEMA3F is one of the microenvironmental factors with a tumor suppressor function." (PMID 29299034, 2017). "Interestingly, only SEMA3F (both the new and the canonical transcripts) are expressed in all analyzed tumor biopsies." (PMID 26784191, 2016). "We could not find any correlation between the expression of both the new and the annotated SEMA3F isoforms—and specific clinical characteristics of BC (i.e., subtypes, tumor stage, hormone receptors’ positivity)." (PMID 26784191, 2016). "Thus, this approach enables circulating SEMA3F production to begin at a time after tumor growth has been established in the mouse." (PMID 26156437, 2015). "This suggests that, as in other tumor types, promoter methylation might be an important mechanism responsible for SEMA3F protein down regulation in tumor cells." (PMID 26447612, 2015). "Therefore, to get further information about the relation between SEMA3F expression and tumor progression, we took advantage of a large series of multifocal ileal NETs." (PMID 26447612, 2015). "In these tumor cells, SEMA3F also blocks their migration induced by CXCL12 and S1P." (PMID 25068647, 2014). "Patterns of gene expression associated with the 2,656-tumor dataset were found in both TCGA datasets, including the low PC4a gene expression signature of high VEGFA and low SEMA3B, SEMA3C, SEMA3F, and PLXNB1." (PMID 23667446, 2013).
tumor (continued). "In a related study, low level of Sema3F expression was observed in highly metastatic human tumor cell lines due to Id2-mediated repression of gene transcription, which possibly accounts for the enhancement of tumor cell migration and invasion." (PMID 23050142, 2012). "Class-3 semaphorins, such as sema3A, sema3B, sema3F have been previously characterized as natural tumor suppressors and there are indications that sema3E also may function as a natural tumor suppressor." (PMID 22936999, 2012). "Moreover, NRP2 is a functional receptor for semaphorin 3F, which was described as an inhibitor of angiogenesis, tumor progression and metastasis." (PMID 21747928, 2011). "By contrast, Sema3F generally regarded a tumor suppressor was down-regulated in P4 cells." (PMID 21559368, 2011). "It follows that semaphorins such as sema3F probably inhibit angiogenesis and tumor cell proliferation simultaneously and may also affect in addition the behavior of additional types of stromal cells." (PMID 18818766, 2008). "We also determined whether sema3D, sema3F and sema3G, which inhibit tumor formation from MDA-MB-435 cells, also inhibit the anchorage free growth of these cells." (PMID 18818766, 2008). "However, it is unclear which of these mechanisms is the primary mechanism used by semaphorins such as sema3F to inhibit tumor development." (PMID 18818766, 2008). "Indeed, sema3F and sema3B have been found to inhibit the adhesion, migration and proliferation of several types of lung cancer derived tumor cells." (PMID 18818766, 2008). "It is thus possible that the inhibition of tumor development from MDA-MB-231 cells by sema3F is mediated by np1 and that it is augmented by the relatively high expression level obtained with sema3F and by the anti-angiogenic effect displayed by sema3F in tumors derived from this cell type." (PMID 18818766, 2008). "The identification of sema3B and sema3F as tumor suppressors, and the identification of sema3F and sema3A as inhibitors of angiogenesis, suggested that additional sema3s may also possess anti-tumorigenic and anti-angiogenic properties." (PMID 18818766, 2008). "The tumors that developed from sema3F expressing MDA-MB-231 cells looked less bloody than the control tumors suggesting that sema3F may inhibit tumor angiogenesis." (PMID 18818766, 2008). "Indeed, sema3s such as sema3F and sema3B were reported to inhibit the adhesion, spreading and proliferation of various types of tumor cells." (PMID 18818766, 2008). "Moreover, the bsAb specifically targets a tumor-suppressive pathway of SEMA3F, which may translate to improved efficacy and fewer side effects than SEMAs." (PMID 41391772, 2025). "Moreover, SEMA3F could be identified as an independent factor for better patient survival in patients with early tumor stage (pT1N0-3, pT1-4N0, pT1N0)." (PMID 39232098, 2024). "Additionally, the SEMA3F/NRP2 pathway may present novel therapeutic avenues if subsequent foundational studies corroborate its purported tumor-suppressive capabilities." (PMID 39232098, 2024). "Additionally, SEMA3F is known to modify the tumor microenvironment." (PMID 39232098, 2024). "Furthermore, SEMA3F could be confirmed as an independent factor for better patient survival in patients with early tumor stage (pT1N0-3: HR = 0.505, p = 0.014, pT1-4N0: HR = 0.664, p = 0.024, pT1N0: HR = 0.483, p = 0.040)." (PMID 39232098, 2024). "The association between SEMA3 gene expressions and tumor stemness score as well as with the drug sensitivity score indicated that SEMA3A, SEMA3C, and SEMA3F may mainly play tumor promotor roles during tumorigenesis as they are positively associated with tumor stemness and drug resistence scores." (PMID 32241267, 2020).
tumor (continued). "The progression of solid tumors depends upon angiogenesis, and it was indeed initially found that sema3F, a semaphorin that utilizes the neuropilin-2 receptor as its primary binding receptor, functions as an inhibitor of angiogenesis and of angiogenesis-dependent tumor progression." (PMID 30696103, 2019). "In addition, we observed that overexpression of SEMA3F could significantly decrease the OSCC tumor volume and weight in vivo." (PMID 29299034, 2017). "This suggests that SEMA3F may be a tumor suppressor in OSCC." (PMID 29299034, 2017). "However, liver metastases developed from STC-S3F2 tumors were rare; at morphometrical evaluation, their surface was significantly reduced as compared to controls suggesting that the expression of SEMA3F could affect tumor progression." (PMID 26447612, 2015). "Contrary to previous reports which observed sema3F and sema3A induced changes in adhesion of tumor cells to fibronectin coated dishes, we could not see any effects of any of the semaphorins we tested on the adhesion to fibronectin of any of the tumor cells used here." (PMID 18818766, 2008). "Of note, primary PCa tumours showed high JAG1, GP2, GLO1, NPR3, VGLL3, CHRNA2 and SEMA3F mRNA levels in primary PCa tissue samples." (PMID 40219635, 2025). "SEMA4G levels were enriched in classical tumours while the expression of SEMA3A, SEMA3C and SEMA3F was significantly enriched in basal-like PDAC." (PMID 38670629, 2024). "The expression of SEMA3F was higher in healthy mucosa than in the tumor (p = 0.015) and, in contrast, the expression of NRP2 was higher in the tumor than in healthy mucosa (p = 0.001)." (PMID 35565388, 2022). "The recruitment of RORA can induce the expression of the tumor suppressor genes F-box/WD repeat-containing protein 7 (FBXW7), Semaphorin 3F (SEMA3F), and P21, leading to apoptosis and suppression of tumor cell proliferation." (PMID 34285836, 2021). "In relation to the malignancy grade of the tumor, mRNA levels of SEMA3B, SEMA3C, SEMA3D, SEMA3G, PLXNA2, and CDH1 decreased while mRNA levels of SEMA3F, NRP1, ITGB3, ITGA5, and VEGFA increased with the increase of the tumor malignancy (p < 0.05)." (PMID 33036421, 2020). "FAM83C-AS1 is upregulated in tumor tissues and cells of CRC, which is negatively correlated with SEMA3F expression." (PMID 33109776, 2020). "Further studies confirmed that the inhibitory activity of Sema3F on GBM cell migration depends on NRP2 expression, suppressed by hypoxia in the tumor context, and on the subsequent RhoA inactivation." (PMID 31052281, 2019). "The same was true of Sema3F, which interacts with NRP2 and inhibits tumor formation and angiogenesis." (PMID 31052281, 2019). "Recent evidence suggests that SEMA3F functions as a PI3K-Akt-mTOR inhibitor in mammalian cells, including T cells, ECs, and tumor cells." (PMID 30532711, 2018). "This means that SEMA3F inhibits the growth ability in SAS and HSC2 cells and acts as a potential OSCC tumor suppressor." (PMID 29299034, 2017). "SEMA3F also inhibits the inducible expression of VEGF at both the transcriptional and protein level in vitro, and it has powerful anti-tumor effects in vivo." (PMID 26156437, 2015). "Our results also suggest that the antitumoral effect of SEMA3F re-expression is likely to be multifactorial and might involve a combination of anti-proliferative and anti-angiogenic effects, as shown by the decrease in Ki67 index and in microvascular surface within tumor tissue." (PMID 26447612, 2015). "This was accompanied by enhanced expression of semaphorin 3F (SEMA3F), a tumor suppressor that inhibits tumor growth and invasiveness." (PMID 26878025, 2015). "Until now TSGs which were isolated from AP20 and LUCA regions (e.g.G21/NPRL2, RASSF1A, RASSF1C, SEMA3B, SEMA3F, RBSP3) were shown to inhibit tumour cell growth both in vitro and in vivo." (PMID 18725949, 2008). "Among class 3 semaphorins, SEMA3A, SEMA3F, and SEMA3C play distinct roles in tumor biology." (PMID 41009819, 2025).
tumor (continued). "Notably, the 3p chromosome change impacts over 500 genes, featuring tumor suppressors like BAP1, FHIT, VHL, PTPγ, SEMA3B, SEMA3F, TUSC2, and MLH1." (PMID 39201328, 2024). "In vitro experimental evidence indicated that the inhibition of aberrant angiogenesis elicited by local or systemic administration of Sema3F in vivo may be mediated by the NRP2-dependent inhibition of VEGF production and Akt-mTOR signaling in tumor cells." (PMID 31052281, 2019). "SEMA3F and netrin-1 have multifaceted effects on tumor and surrounding non-tumor cells, including ECs, leukocytes, macrophages, and fibroblasts." (PMID 30532711, 2018). "Interestingly, three of the ligands with reduced expression in high PC3a and low PC4a samples, SEMA3B, SEMA3F, and SEMA3G, had both anti-angiogenic and tumor suppressor functions." (PMID 23667446, 2013). "Surprisingly, we did not observe inhibition of tumor development following the expression of sema3G, which like sema3F binds to np2, or following expression of sema3B which binds to both of the neuropilins." (PMID 22936999, 2012). "The second example was the successful inhibition by sema3F of tumor formation from MDA-MB-231 cells which express np1 but not np2 and thus should not have been inhibited by sema3F." (PMID 18818766, 2008). "SEMA3F shows growth inhibitory activity in SAS and HSC2 cells and may act as a tumor suppressor." (PMID 29299034, 2017). "Expression of sema3A inhibited significantly tumor development while expression of sema3F did not." (PMID 18818766, 2008). "For example, sema3F did not inhibit the formation of colonies from MDA-MB-435 cells despite the presence of np2 receptors in these cells even though it inhibited strongly tumor formation." (PMID 18818766, 2008). "We also determined whether expression of sema3A and sema3F, the best studied np1 and np2 agonists respectively, inhibits tumor development from the non-metastatic, estrogen dependent, np1 expressing MCF-7 cells." (PMID 18818766, 2008). "Interestingly, SEMA3F does not have an impact on patients' survival in more advanced tumor stages." (PMID 39232098, 2024). "Notably, we could not find any correlation between the expression of new SEMA3F isoform and tumor sbtype, stage and/or positivity to ER or PR." (PMID 26784191, 2016). "Western blotting experiments showed that HT29ctrl and HT29NRP2 express the same level of semaphorin 3F, whereas no semaphorin 3F was found in Colo320 cells, suggesting that NRP2-mediated tumor proliferation does not involve semaphorin 3F." (PMID 21747928, 2011). "Interestingly, although the rest of SEMA3 family members showed significant negative correlation with tumour stem-cell-like features measured by mRNA (RNAss) and DNA methylation (DNAss), expression of SEMA3A, SEMA3C, and SEMA3F were not significantly correlated with RNAss." (PMID 32241267, 2020).